MVP (major vault protein)
Diseases named in the same sentence as MVP in open-access papers (continued):
Sharing a sentence is not in itself a finding about the gene and the disease.
tumor (continued). "Fittingly, in our study, TNFα was a strong stimulator of vault RNA, MVP, and TEP1 gene expression and also MVP protein expression in the TNFα-responsive BON tumor model." (PMID 36980669, 2023). "The KD of MVP stimulated STAT3 (signal transducer and activator of transcription 3) and accelerated tumor growth." (PMID 35681764, 2022). "Knockdown of MVP or treatment with GANT61 significantly inhibited tumor growth, however, combined inhibition of MVP and GLI1 showed additive synergistic anti-tumor effect." (PMID 33637972, 2021). "In particular, to deliver greater amounts of DNA to the nucleus in multidrug-resistant tumor cells using PAMAM-NH2, we suggest the codelivery of siRNA-MVP or an inhibitor to decrease the nuclear efflux generated by MVP." (PMID 33980270, 2021). "The present research also revealed that MVP, as a crucial GLI1 regulator enhances proliferation to tumor cells and anti-apoptosis process." (PMID 33637972, 2021). "Especially, to provide more DNA to the nucleus and enhance DNA transfection efficiency in multidrug-resistant tumor cells using PAMAM-NH2, siRNA-MVP or an inhibitor should be codelivered to decrease MVP-mediated nuclear efflux." (PMID 33980270, 2021). "Interestingly, the up-regulation of MVP has also been found in other situations including chemotherapy resistance, malignant transformation, as well as exposure to diverse antineoplastic drugs, suggesting the complexity in regulation of MVP expression in tumor cells." (PMID 31092229, 2019). "Taken together these data suggest that MVP induces pro-survival and pro-migratory phenotypes in GBM cells leading to enhanced tumour aggressiveness in vivo." (PMID 24243798, 2013). "Subsequently, to corroborate these observations, we examined the protein levels of MVP in 10 primary PAAD tumor tissues and 10 matched adjacent normal tissues." (PMID 39026679, 2024). "It is thought that MVP, along with other ABC transporters and pumps on cell membranes, can either shuttle drugs away from cells or detoxify chemical compounds, thus protecting the cells and allowing tumor progression." (PMID 34349149, 2021). "While detected in the cellular tumor in a subgroup of patient tumors, Mo (CL7) and BAM (CL8) signatures were particularly evident in niches with blood–brain barrier leakage, including HyBV, MvP, perinecrotic, and pseudopalisading areas, in line with our findings in PDOXs and GL261." (PMID 38566128, 2024). "Interestingly, MVP was more expressed in correspondence of tumor cells present in the tumor periphery rather than in the tumor center." (PMID 31569710, 2019). "Thus, we investigated the intricate relationship between MVP expression levels and the dynamic distribution of immune cells at the single-cell level through the TISCH website, showing a higher proportion of malignant cells in tumor tissues than that in normal tissues." (PMID 39026679, 2024). "Twenty out of the 30 patients (66.7%) suffering tumour stages III-IV and negative or fairly positive MVP expression were alive, while 12 out of the 36 patients (33.3%) with tumour stages III-IV and overexpression of MVP were alive." (PMID 22931894, 2012).
infection (12 papers, 2007 to 2024). The state of being infected such as from the introduction of a foreign agent such as serum, vaccine, antigenic substance or organism. "Our study reveals that MVP has the potential to serve as a diagnostic biomarker for both inflammation and infection." (PMID 39338437, 2024). "Infection caused by Listeria monocytogenes has also been shown to increase MVP expression, that in turn masks intracytosolic pathogens from autophagic recognition and clearance." (PMID 37301807, 2023). "The mean levels of MVP in patients with infection (2139 ± 265 pg/mL) were about two-fold increased as compared to patients with no infection (1160 ± 132 pg/mL)." (PMID 39338437, 2024). "MVP was found to be enhanced during infection with viruses, including the hepatitis C virus (HCV), vesicular stomatitis virus (VSV), influenza A virus (IAV), enterovirus 71 (EV71), and HBV." (PMID 39338437, 2024). "It will be thus of the highest importance to decipher in which cells InlK is expressed in vivo and when the InlK/MVP interaction takes place during infection." (PMID 21829365, 2011). "The aim of this study was to assess the diagnostic and prognostic value of major vault protein (MVP) in patients with inflammation, in order to determine whether MVP could be used as a biomarker for infection or inflammation." (PMID 39338437, 2024). "Interaction of EseN with the scaffold protein MVP could regulate selection of MAPKs for dephosphorylation during the infection." (PMID 37796003, 2023). "Recent studies have shown that the infection of several viruses upregulates MVP expression, including hepatitis C virus (HCV), vesicular stomatitis virus (VSV), influenza A virus (IAV), enterovirus (EV71), hepatitis B virus (HBV) and human immunodeficiency virus (HIV)." (PMID 34835073, 2021). "Hepatitis B virus (HBV) infection suppresses MVP–mediated type I IFN production in vitro." (PMID 34835073, 2021). "Infection of MVP-transfected epithelial cells with ΔactA and ΔactA+inlK led to similar results." (PMID 21829365, 2011). "To investigate this, we infected HeLa cells with reduced or enhanced expression levels of DDAH1 with Listeria at a multiplicity of infection (MOI) of 25, measuring the effect of CYR61 and MVP in parallel." (PMID 34804992, 2021). "These include an increased number of vaults in immune cell types, IFN-upregulation of MVP, the major component of vaults, and upregulation of noncoding vault RNAs (vRNAs) on infection with pathogens such as Epstein-Barr virus." (PMID 24875882, 2014). "MVP co-localized with Pseudomonas aeruginosa in lung epithelial cells at an early stage of infection, and MVP knockout mice, which do not form vault particles, were shown to be more susceptible to bacterial lung infection." (PMID 18044992, 2007). "After confirming successful lentiviral infection (i.e., 80% infection) with green fluorescent protein (GFP) expression, we further validated transfection with immunostaining, qRT-PCR and Western blot, which all confirmed the reexpression of MVP in the Lv-MVP-infected group." (PMID 34158848, 2021).
adenocarcinoma (4 papers, 2009 to 2021). A common cancer characterized by the presence of malignant glandular cells. "The association of high expression of MVP with better clinical outcome in adenocarcinoma may be attributed partly to the suppressive effect of MVP on STAT3 signaling pathway." (PMID 31092229, 2019). "MVP expression was independent of clinical and histological variables, except for adenocarcinoma tumors." (PMID 19660100, 2009).
metabolic disease (3 papers, 2019 to 2022). A congenital disorder (due to inherited enzyme abnormality) or acquired (due to failure of a metabolically important organ) disorder resulting from an abnormal metabolic process. "Our previous studies indicated that major vault protein (MVP) deficiency was accompanied by suppressed phosphorylation of AKT in metabolic diseases." (PMID 35246039, 2022). "To explore the mechanisms underlying the antagonizing effects of MVP on metabolic disorders, we examined the relationship between MVP deficiency and inflammation." (PMID 30996248, 2019). "The exacerbated metabolic disorders caused by MVP deficiency are accompanied with increased macrophage infiltration and heightened inflammatory responses in the microenvironments." (PMID 30996248, 2019). "Besides, our previous studies showed that MVP deficiency was accompanied by suppressed phosphorylation of AKT in metabolic diseases." (PMID 35246039, 2022). "Major vault protein (MVP) is known to promote apoptosis and prevent metabolic diseases in macrophage." (PMID 34158848, 2021). "By using several animal models of metabolic diseases, we identify macrophage MVP as an important suppressor of NF-κB activation by preventing TRAF6 ubiquitination." (PMID 30996248, 2019). "The discovery of MVP-mediated negative regulation of NF-κB may pave the way for clinical intervention strategies for metabolic diseases." (PMID 30996248, 2019). "Conceivably, the autonomous negative regulation of TRAF6 by different factors including MVP may determine the precise role of IKK and as such the outcomes in the metabolic diseases." (PMID 30996248, 2019).
Bacterial infection (2 papers, 2021 to 2023). "An increase in MVP expression is observed in humans in the innate response during both viral and bacterial infection." (PMID 37301807, 2023). "MVP protein is also involved in the immune response in bacterial infections." (PMID 37301807, 2023).
neurodevelopmental disorder (2 papers, 2023). A behavioral and cognitive disorder with onset during the developmental period that involves impaired or aberrant development of intellectual, motor, or social functions. "The MAPK3 gene (encoding ERK1) and the major vault protein gene (MVP), both involved in the ERK/MAP kinase pathway, are associated with neurodevelopmental disorders." (PMID 38203422, 2023). "We also confirm MVP implication in the ERK1 signaling pathway in vivo and define MVP as a novel candidate gene in male-specific neurodevelopmental disorders." (PMID 37968726, 2023).
inflammatory myopathies (1 paper, 2022). "In inflammatory myopathies, GRN, MVP and NFYB showed high diagnostic value, while RNF128, ERP29 and KPNA3 showed poor diagnostic value, indicating high inflammation activation but little involvement of protein homeostasis." (PMID 36203997, 2022).
MVP also shares sentences with these, for which no sentence is quoted: cervical carcinoma (2 papers); chondrosarcoma (2); frontal lobe epilepsy (2); squamous cell carcinoma (2); stomach cancer (2); thyroid cancer (2); alcohol (1); autism (1); autoimmune disease (1); bone osteosarcoma (1); digestive system cancer (1); eosinophilia (1); fibrosarcoma (1); ganglioglioma (1); giant cell tumor (1); hyperlipidaemia (1); infectious disease (1); Insulin resistance (1); Listeria infection (1); lymphoma (1); melanoma (1); metastatic tumors (1); neuroblastoma (1); neuroendocrine lung tumors (1); neurological diseases (1); non-small cell lung carcinoma (1); oropharyngeal squamous cell carcinoma (1); pancreatic adenocarcinoma (1); pancreatitis (1); polymyositis (1).
A further 4 diseases each share a sentence with MVP in 1 paper.